STAT3 (signal transducer and activator of transcription 3)
Diseases named in the same sentence as STAT3 in open-access papers (continued):
Sharing a sentence is not in itself a finding about the gene and the disease.
tumor (continued). "When mimics of these miRNAs are transfected into CD4+ T cells, they induce an imbalance in Treg/Th17 cell populations via STAT3 signaling, leading to an immunosuppressive microenvironment at the tumor site, which facilitates tumor progression and metastasis." (PMID 40612677, 2025). "GDE also contain components of the signal transducer and activator of transcription 3 (STAT3) signaling pathway, which is strongly associated with immune suppression and enhanced tumor growth." (PMID 40075663, 2025). "This leads to an increase in the levels of IL-6 in the tumor microenvironment, and by activating the signal transducer and activator of the transcription 3 (STAT3) signaling pathway, it confers upon macrophages the ability to promote tumor growth." (PMID 40563450, 2025). "In a pre-clinical NSCLC in vivo model, AZD4205 treatment inhibited both tumour growth and STAT3 activation." (PMID 40407951, 2025). "IL6 via the JAK/STAT3 pathway enhances the expression of hypoxia-inducible factor 1-alpha (HIF1α) under hypoxic and acidic conditions at tumor sites, leading to increased VEGF-A expression, which drives neovascularization and angiogenesis." (PMID 40427188, 2025). "In obese mouse, compared with the contralateral adipose tissue of the tumor, the ipsilateral adipose tissue of the tumor activated the STAT3/NF-κB p65 signal pathway and increased IL6 secretion." (PMID 40841364, 2025). "This suggests that the deficiency of miR-214-3p mediates the upregulation of IKBKB, which subsequently activates IL6/JAK/STAT3 signaling, thereby promoting tumor progression." (PMID 41044672, 2025). "In multiple tumor models, STAT3 inhibition reduces immunosuppressive myeloid populations, increases effector T cell and dendritic cell infiltration, and enhances responsiveness to immune checkpoint blockade." (PMID 40949156, 2025). "In TNBC, persistent activation of the JAK/STAT signaling pathway—particularly the STAT3 transcription factor—plays a central role in maintaining an immunosuppressive tumor microenvironment and driving resistance to therapy." (PMID 40936705, 2025). "Further, M2-TAMs are involved in the development of therapeutic resistance in tumors by different mechanisms, including activation of STAT3 in tumor cells, enhancing EMT, and upregulating checkpoint inhibitors." (PMID 40805183, 2025). "This is consistent with previous studies in which IL-17 promotes PD-L1 expression in tumor cells by activating STAT3 signaling and recruiting both myeloid suppressor cells (MDSCs) and regulatory T cells (Tregs) to form an immunosuppressive microenvironment." (PMID 40568599, 2025). "A recent study has shown that upregulation of fibroblast monoamine oxidase A in the tumor stroma induces the tumorigenic phenotype of fibroblasts and promotes PCa cell proliferation and stemness marker expression of PCSCs through the IL-6/STAT3 pathway." (PMID 39711287, 2025). "B7-H3 modulates glycometabolism in neuroblastoma through the Stat3/c-Met pathway, thereby promoting tumor cell migration and invasion." (PMID 40519928, 2025). "Our study adds another level of STAT3 activity regulation in tumor cells, namely, the regulation of STAT3 stability/degradation." (PMID 39412616, 2025). "In HER2-positive BC, IL6 induces the production and maintenance of BC stem cells through the NF-κB p65 and STAT3 signal pathways, promoting tumor progression." (PMID 40841364, 2025). "STAT, a transcription factor involved in regulating cellular proliferation and differentiation, is considered one of the most compelling anti-tumor targets, with STAT3 being particularly prominent." (PMID 40949156, 2025). "Overactivation of STAT3 is also attributed to the presence of cancer stem cells (CSCs) or tumor‐initiating cells (TICs), which contribute to drug resistance, tumor metastasis, and recurrence." (PMID 40860906, 2025). "Elevated tumor glycolysis attracts monocytes/macrophages via the ENSA-K63la/SRC-pS12/STAT3-pY705/CCL2 axis." (PMID 39883522, 2025).
tumor (continued). "For example, persistent IL-6/STAT3 signaling within the tumor microenvironment induces DNMT1 and EZH2 expression, thereby reinforcing the epigenetic repression of tumor suppressor genes and maintaining a pro-oncogenic inflammatory state." (PMID 41226277, 2025). "Recent research has demonstrated that lactate drives macrophage remodeling by inhibiting RARγ expression, enhancing interleukin-6 levels in the tumor microenvironment, and activating the STAT3 signaling pathway to promote CRC progression." (PMID 40900785, 2025). "This fusion, involving the KIF5B and ALK genes, creates an oncogenic kinase that activates downstream pathways, such as STAT3, promoting tumor growth, migration, and invasion." (PMID 39810398, 2025). "By downregulating PRLR, Osthole disrupts the ligand-dependent activation of JAK2, leading to reduced STAT3 phosphorylation — a critical event in tumor cell proliferation and resistance to apoptosis." (PMID 40978029, 2025). "To delineate the immunoregulatory hierarchy of the YTHDF3/m6A/STAT3 axis in tumor-immune crosstalk, we engineered Ythdf3 knockout (Ythdf3−/−) mice through CRISPR/Cas9-mediated editing and established TC-1 xenograft models." (PMID 41453852, 2025). "This provides evidence for the novel regulatory role of tumor-derived exosomal lncRNA HEIH targeting the miR-98-5p/STAT3 axis in macrophages, aiding the understanding of the complex interactions between the TME and immune cells in HCC treatment." (PMID 40352941, 2025). "Endocytosed sVASN enhanced the nuclear translocation of p-STAT3(Tyr705), leading to the activation of a cascade of genes, ultimately contributing to tumor malignant progression." (PMID 40430053, 2025). "Their results also indicated a significant increase in expression of IL6 and STAT3 in tumor biopsies." (PMID 40895532, 2025). "IL-6 activates JAK/STAT3 signaling pathway to promote inflammatory responses and support tumor progression." (PMID 40255422, 2025). "STAT3 mediates a broad array of cellular functions, including immune regulation, tumor progression, tumor inflammation, and metabolic reprogramming, with tissue-specific responses across various disease contexts." (PMID 40704145, 2025). "Our findings indicate that the NLP-EXOSOME COMPLEX-STAT3-silencer delivery system only reached a small fraction of tumor cells, as evidenced by the reduction in STAT3-mRNA expression at the tumor site." (PMID 40427146, 2025). "Tumor-associated macrophages and fibroblasts secrete cytokines that transform normal tumor cells into CSCs via TGF-β1, STAT3/Sox2, JAK2/STAT3/snail, notch/STAT3, and IGF-II/IGF1R pathways." (PMID 39753364, 2025). "While we did not perform formal immune cell deconvolution using tools such as CIBERSORT or xCell, the activation of STAT3 and NF-κB signaling in PGC provides strong transcriptional evidence for an inflammation-associated tumor microenvironment." (PMID 40862793, 2025). "Lastly, BP1003 is a novel anticancer therapeutic that targets STAT3, a protein involved in promoting tumor growth, drug resistance, and immune evasion." (PMID 40330466, 2025). "Tumor cells induce M2 macrophage polarization via multiple pathways, including NF-κB, STAT3, and hypoxia-related mechanisms, thereby intensifying the malignant characteristics of the tumor." (PMID 40028322, 2025). "Specifically, IL-6 induces an immunosuppressive state via the JAK1/STAT3 pathway, which inhibits cytotoxic T-cell differentiation and anti-tumor activity." (PMID 41019062, 2025). "The JAK2/STAT3 pathway plays significant roles in tumorigenesis and tumor progression across multiple cancer types." (PMID 40649917, 2025). "Since 72 h, tumor increment was surveyed in HT-29 cells treated by hAMSCs through the EGFR/c-Src/IRSp53/p-AKT/p-Stat3/cyclin D1 signaling cascade." (PMID 41200137, 2025).
tumor (continued). "These miRNAs disrupt the balance between regulatory T cells (Tregs) and T helper 17 (Th17) cells by inhibiting the signal transducer and activator of the transcription 3 (STAT3) pathway, further promoting an immunosuppressive tumor microenvironment." (PMID 40284522, 2025). "IL-6 demonstrates context-dependent effects, promoting both inflammation and tumor progression through signal transducer and activator of transcription 3 (STAT3) signaling." (PMID 40806379, 2025). "Compared to the model group, the expression levels of p-STAT3/STAT3 proteins in the tumor tissues of the Nolvadex, RRTS-H, and RRTS-M groups were significantly reduced (P < 0.01), while those in the RRTS-L group was notably reduced (P < 0.05)." (PMID 40351419, 2025). "TAMs also activate tumor cells through a mutagenic environment, pro-inflammatory mediators, and transcription factors like STAT3 and NF-κB." (PMID 40260236, 2025). "Among these, the MAPK/ERK and STAT3 pathways play key roles in promoting tumor progression, immune evasion, and resistance to immunotherapy." (PMID 40843361, 2025). "Extensive research confirms that STAT3 is aberrantly activated in many cancer cells, linking it directly to tumorigenesis, with tumor growth being regulated by STAT3 and its downstream targets." (PMID 40906092, 2025). "Pro-inflammatory cytokines, such as TNF-α, IL-6, and IL-11, mediate the tumor-promoting function of M2 macrophages in cancer cells by activating the NF-κB/STAT3 pathways." (PMID 40422244, 2025). "The activated JAK2/STAT3 pathway is involved in the pathologies of cancer and inflammatory diseases, and it promotes carcinogenesis, tumor development, cancer cell survival, and the spread of solid tumors." (PMID 40018404, 2025). "Although TAMs represent a heterogeneous population, they are often M2-polarized macrophages differentiated under the influence of tumor stromal immune cues that activate the JAK/ STAT3 signaling pathway." (PMID 41008624, 2025). "IL6 activates STAT3 signaling, contributing to tumor progression, chemotherapy resistance, and immune evasion.It enhances survival and promotes cell migration." (PMID 40427188, 2025). "The STAT3 signaling pathway is crucial for maintaining the M2 phenotype of TAMs across various tumor models." (PMID 40607254, 2025). "STAT3 likewise is important for regulatory T cell (Treg) differentiation via TGFβ, and deletion of STAT3 in the murine T cell compartment obliterates Treg tumor infiltration." (PMID 40356899, 2025). "Consistent with the in vitro results, the combined inhibition of Notch1 and STAT3 induced a more potent delay in tumor growth and reduced tumor volume." (PMID 40019515, 2025). "NF-κB and IL-6/STAT3 form an inflammatory positive-feedback loop that promotes tumor survival and proliferation, while suppressing antitumor immunity and compromising microbicidal defenses at mucosal barriers." (PMID 41463208, 2025). "GSEA hallmark analysis also revealed that hallmarks of interferon-gamma response and IL6_JAK_STAT3 pathway were downregulated in old tumor cells." (PMID 41332581, 2025). "In conclusion, elevated glycolysis levels in PDAC promote ENSA-K63la, a crucial step that triggers STAT3/CCL2 signaling in tumor cells." (PMID 39883522, 2025). "An interesting line of inquiry is the function of STAT-3 in modifying the tumor microenvironment, specifically by recruiting immunosuppressive cells." (PMID 40227645, 2025). "In cancer, aberrantly active STAT3 drives oncogenic programs, promoting cell-cycle progression, uncontrolled proliferation, resistance to apoptosis, and tumor neoangiogenesis." (PMID 41031165, 2025). "Overexpression of STAT3 enhances tumor resistance to radiotherapy by promoting DNA repair, inhibiting apoptosis, and sustaining cancer stem cell survival." (PMID 41326498, 2025). "One study found that FTO works by inhibiting growth and glycolysis, likely by reducing the expression of APOE which acts to promote tumor growth via the IL-6/JAK2/STAT3 pathway." (PMID 40243425, 2025).
tumor (continued). "Immune cells like TAMs, neutrophils, and lymphocytes secrete pro-inflammatory cytokines (e.g., IL-6, TNF-α, IL-1β) that activate NF-κB and STAT3 signaling, enhancing tumor proliferation, survival, and metastasis." (PMID 41311372, 2025). "Previous studies have shown that tumor-associated macrophages can secrete inflammatory cytokines such as TNF-α and IL-6, activating the STAT3 signaling pathway and thereby promoting chemotherapy resistance in OS cells." (PMID 41285805, 2025). "Considering that NB represent a tumor characterized by impaired neuronal differentiation, we can speculate that non-coding variants located in regulatory elements associated with both STAT3 and SIN3A transcriptional regulation could impact neuronal development." (PMID 39843641, 2025). "Persistent hepatic inflammation in Child–Pugh B patients can also activate pathways like IL-6/STAT3 and IL-17, promoting tumor cell proliferation, invasion, and drug resistance." (PMID 40481877, 2025). "In vitro, it inhibits proliferation and induces G2/M cell cycle arrest in ovarian, liver and pancreatic cancer cell lines and suppresses STAT3 activation, which is commonly involved in tumor growth and immune evasion." (PMID 41465505, 2025). "In non-tumor diseases, STAT3 can either promote ferroptosis, exacerbating tissue damage, or inhibit ferroptosis to maintain cellular homeostasis." (PMID 40371332, 2025). "This comprehensive mechanism reveals how BE-43547A2 precisely targets the hypoxic tumor microenvironment through the multi-level regulation of the eEF1A1-FoxO1-JAK/STAT3 signaling cascade." (PMID 40806463, 2025). "TLR9 promotes the expression of PD‐L1 by regulating STAT3 signaling and enabling tumor cells to escape immune surveillance." (PMID 40727252, 2025). "These in vivo data conclusively demonstrate RNLS’s oncogenic role through STAT3-dependent modulation of tumor growth and redox balance." (PMID 40799250, 2025). "This antagonistic interaction between STAT1 and STAT3 is crucial for understanding their complex roles in the biology of neoplasms and highlights potential therapeutic targets for modulating these pathways." (PMID 40287766, 2025). "Constitutive activation of JAKs sustains persistent STAT3 phosphorylation, which in turn promotes key oncogenic processes, including tumor cell proliferation, survival, metastasis, immune evasion, and chemoresistance." (PMID 41585878, 2025). "Epigenetic modifications suppress anti‐tumor genes such as RARγ while activating immunosuppressive IL‐6/STAT3 signaling." (PMID 40904700, 2025). "Apart from STAT3, aggressive tumor formation is also significantly influenced by focal adhesion kinase (FAK), an overemphasized tyrosine kinase in tumor cells that can govern cell survival, multiplying, and immigration." (PMID 40217305, 2025). "Its capacity to promote tumor cell proliferation, activate oncogenic signaling pathways such as STAT3, facilitate immune suppression, and stimulate angiogenesis underscores its active participation in tumor biology." (PMID 41425077, 2025). "Chronic P.g. infection increases IL-6 secretion via TLR signaling, which activates STAT1 and STAT3, driving tumor progression through a feedback loop involving CXCL10, PD-L1, and GAS6 genes." (PMID 40924302, 2025). "Aging cells secrete inflammatory factors (such as IL-1α and IL-6) through SASP, which intensifies local inflammatory response and promotes the proliferation of tumor cells by activating NF-κB and STAT3 pathways." (PMID 40951350, 2025). "Dysbiosis-associated ligands (e.g., LPS, flagellin) activate TLRs to drive NF-κB and IL-6/STAT3 signaling, thereby amplifying tumor fitness, blunting antitumor immunity, altering antimicrobial-peptide programs, and increasing epithelial permeability." (PMID 41463208, 2025). "This STAT3-centirc program is well-aligned with established mechanisms underlying myeloid-derived suppressor cell (MDSC) expansion and tumor-associated macrophage (TAM) polarization." (PMID 41514627, 2025).
tumor (continued). "The molecular mechanisms underlying these effects were further explored by focusing on the JAK2/STAT3 signaling axis, which has been shown to play a critical role in tumor cell migration, invasion, and metastasis." (PMID 40075566, 2025). "The STAT3 protein regulates tumor invasion and suppression of apoptosis, and the upregulation of this marker is linked to epithelial-to-mesenchymal transition." (PMID 40149331, 2025). "STAT3 subsequently transduces the signal, resulting in IL-6 and IL-10 production, therefore amplifying this chronic pro-inflammatory loop and inducing tumor growth." (PMID 41463071, 2025). "Activation of the STAT3 pathway in neutrophils leads to the overexpression of PD-L1, which inhibits the function of cytotoxic T lymphocytes and weakens the anti-tumor response." (PMID 40563651, 2025). "Targeting components of this pathway, such as STAT3, represents a promising therapeutic strategy to disrupt the tumor-supportive functions of neutrophils while potentially reprogramming them to adopt anti-tumorigenic properties." (PMID 40486614, 2025). "STAT3 activation promotes tumor angiogenesis in a variety of tumor types by upregulating the production of vascular endothelial growth factor (VEGF) and metalloproteinases (MMPs)." (PMID 41068541, 2025). "Higher STAT3 activity in proximal tumors links to inflammation-driven tumor microenvironment, advanced stage, and poorer survival." (PMID 40862793, 2025). "Western blot analysis of tumor tissues showed a marked decrease in phosphorylated Jak2 and Stat3, as well as reduced Vegfa expression, in Prkci knockout tumors compared to controls." (PMID 40840329, 2025). "Meanwhile, SMARCB1 deletion led to the upregulation of the IL6/JAK/STAT3 signaling pathway, which activated the transcriptional activity of STAT3 and enhanced the proliferative and invasive abilities of tumor cells." (PMID 39995416, 2025). "In this model, tumor LDHA was shown to upregulate CCL2/CCL7 via the ERK → YAP1/STAT3 pathway, thereby recruiting macrophages." (PMID 41463052, 2025). "STAT3 regulates M2 macrophages to facilitate tumour growth by promoting immune evasion, supressing immune responses, and enhancing angiogenesis." (PMID 40407951, 2025). "In contrast, IL-10 and TGF-β promote M2 polarization via STAT3 and Smad signaling, increasing arginase-1 and PD-L1 expression, suppressing anti-tumor immunity." (PMID 41244711, 2025). "The pivotal role of STAT3 in oncogene expression underscores the potential clinical significance of targeting U-STAT3 for tumor treatment." (PMID 40725945, 2025). "For example, in pancreatic cancer, the upregulation of L1CAM in tumour-associated endothelial cells (TECs) enhanced IL-6 expression, activating the JAK/STAT3 signaling pathway, which in turn triggered EndMT associated with tumour progression and metastasis." (PMID 40083695, 2025). "The intelligent HMP1G NPs respond to H+ and glutathione in the tumor microenvironment (TME), They downregulate tumor‐derived IDO1 via the AhR/STAT3/IL axis, improve the KYN/TRP metabolic imbalance, and effectively counter immunosuppression in the TME." (PMID 39661740, 2025). "Experimental inhibition of NF-κB and STAT3 in prostate cancer resulted in tumour growth arrest and prevented cancer stem cells from thriving." (PMID 41009413, 2025). "The activation and phosphorylation of STAT3 (pSTAT3) stay elevated from the hyperplastic dysplasia stage through to the tumor stages." (PMID 40548181, 2025). "The Janus kinase (JAK)/STAT axis, particularly STAT3, enhances survival signaling and immunosuppressive tumor microenvironment, correlating with poor prognosis." (PMID 41373772, 2025).